APOE (apolipoprotein E)
Diseases named in the same sentence as APOE in open-access papers (continued):
Sharing a sentence is not in itself a finding about the gene and the disease.
multiple sclerosis (45 papers, 2006 to 2026). A progressive autoimmune disorder affecting the central nervous system resulting in demyelination. "Large-scale human studies have disputed the association between APOE and multiple sclerosis (MS), whereas the impact of APOE*ε2 on Huntington disease (HD) remains elusive." (PMID 33148290, 2020). "Evidence from a meta-analysis of 6977 subjects provides evidence that APOE E2 mutation is associated with multiple sclerosis risk." (PMID 26830841, 2016). "A meta-analysis of 6977 subjects provides evidence that APOE E2 mutation is associated with multiple sclerosis risk." (PMID 24456740, 2014). "In this review, we outlined the immuno-modulatory properties of apoE, with special focus on the association of APOE ε allele with the clinical features of multiple sclerosis (MS) and of its animal model experimental autoimmune encephalomyelitis (EAE)." (PMID 20613949, 2010). "Given previous reports of greater risk effects of DR15 in female patients with multiple sclerosis (MS) and the stronger effect of APOE ɛ4 in females, we assessed whether men versus women showed similar or different HLA haplotype associations with AD risk." (PMID 28350795, 2017). "In addition to its well-established role in lipid transportation and atherosclerostic pathogenesis, apoE bears immunomodulatory properties and is associated with multiple sclerosis (MS) and psoriasis." (PMID 21772670, 2011). "These include, for example, marker genes for disease-associated microglia (DAM), the microglia neurodegenerative phenotype (MGnD), and microglia inflamed in multiple sclerosis (e.g., APOE, CLEC7A, TREM2, CD68)." (PMID 40700130, 2025). "Inheritance of APOE alleles is associated with varying clinical outcomes in several neurodegenerative diseases, including AD, PD, ALS, head trauma, multiple sclerosis, and HIV-encephalitis." (PMID 16603079, 2006). "Removing the APOE region had minimal effect on the pair-wise genetic correlations and their significance, with the exception of identifying a new significant correlation for Multiple Sclerosis (cor = − 0.23, SE = 0.06, FDR = 7.3 × 10–03)." (PMID 37101235, 2023). "We aimed to find an association between optic neuritis with and without multiple sclerosis and the APOE allele and APOE serum levels." (PMID 35885971, 2022). "This study aimed to evaluate the association of ON (with and without multiple sclerosis) with APOE alleles and APOE serum levels." (PMID 35885971, 2022). "This study aimed to compare the genotypes and allele frequencies of the APOE in different groups of ON: ON without multiple sclerosis vs. the control group and ON with multiple sclerosis vs. the control group." (PMID 35885971, 2022). "Previous study indicated that direct protein-protein binding effects of apoE with its signal receptor LRP1 enable microglia to exert immunosuppressive and neuroprotective effects in neuroinflammation caused by hemorrhagic stroke, traumatic brain injury, and multiple sclerosis." (PMID 36035210, 2022). "However, APOE is also upregulated in the neurodegeneration-associated microglia in the brain in a variety of neurodegenerative disease mouse models, including AD, ALS, and multiple sclerosis." (PMID 32614373, 2020). "–22 While APOE is expressed more broadly, recent work has found that APOE is upregulated in microglia in mouse models of neurodegenerative disease, including AD, ALS, and multiple sclerosis." (PMID 32614373, 2020). "Despite pleiotropic immunomodulatory effects of apolipoprotein E (apoE) in vitro, its effects on the clinical course of experimental autoimmune encephalomyelitis (EAE) and multiple sclerosis (MS) are still controversial." (PMID 26669675, 2015).
epilepsy (44 papers, 2012 to 2026). A brain disorder characterized by episodes of abnormally increased neuronal discharge resulting in transient episodes of sensory or motor neurological dysfunction, or psychic dysfunction. "Beyond epilepsy, APOE regulation and polymorphisms play crucial roles in neurodegenerative diseases, such as Alzheimer's and Parkinson's diseases." (PMID 41085045, 2026). "Apolipoprotein E (APOE) gene, considered as a genetic factor of AD, is also associated with epilepsy." (PMID 40405274, 2025). "The proportion of APOE ε4 allele is higher in people with epilepsy, especially those with temporal lobe epilepsy (TLE), compared to normal people." (PMID 40405274, 2025). "Our study demonstrated the synergistic effect of APOE ε4 allele and high seizure frequency on worse cognitive function in older people with epilepsy." (PMID 40405274, 2025). "APOE has also been associated with increased neuroinflammation, which is a key factor in the development of epilepsy." (PMID 39727961, 2024). "A recent meta-analysis showed that the ε4 allele of APOE, a known risk factor for AD, is also a risk factor for epilepsy with the epilepsy risk increasing with the number of ε4 copies." (PMID 38263073, 2024). "More sample sizes are required to confirm the potential role of ApoE isoforms in the susceptibility to diverse types of epilepsy from different origins." (PMID 34795746, 2021). "Large-scale publications are required to verify the role of more ApoE variants in the risk of cases with different types of epilepsy in other regions." (PMID 34795746, 2021). "For example, different levels of neuroinflammation associated with epilepsy were directly correlated with a specific APOE genotype in adult patients." (PMID 30677746, 2019). "Tissue samples from temporal lobes resected from epilepsy patients carrying two APOE ε3 alleles were examined regarding an association between inheritance of these alleles and determinants of neuronal resilience." (PMID 22502727, 2012). "Epilepsy is associated with precocious development of Alzheimer-type neuropathological changes, and the APOE ε4 genotype has been associated with further risk of development of such changes." (PMID 22502727, 2012). "The relationship between the APOE ε4 allele and seizure frequency is based on a myriad of complex mechanisms, encompassing neuronal function, Aβ peptide generation, and the pathophysiology of epilepsy." (PMID 40405274, 2025). "The synergistic effect of APOE ε4 allele and seizure frequency on cognitive function suggested their importance in clinical assessments and therapeutic approaches in managing older people with epilepsy." (PMID 40405274, 2025). "Furthermore, we demonstrated the synergistic effect of APOE ε4 allele and seizure frequency on cognitive function in older people with epilepsy." (PMID 40405274, 2025). "The R47H variant of the TREM2 gene, associated with a 2–4-fold increased risk of AD, has been found to elevate epileptic activity in mouse models Genetic studies have identified multiple genes, including APOE, that are implicated in common pathogenetic mechanisms between AD and epilepsy." (PMID 38999445, 2024). "The gene variants of APOE could contribute to epilepsy risk through this neuroinflammation mechanism, especially in the elderly population." (PMID 39727961, 2024). "Thus, neurons in patients with TLE carrying the APOE ε4 allele are less resistant to damaging hyperexcitability associated with epilepsy than APOE ε3 carriers." (PMID 39337715, 2024). "Importantly, several studies have provided evidence that inheritance of an APOE ε4 allele is associated with increased risk for Alzheimer neuropathological changes in epilepsy patients." (PMID 24252240, 2013). "In addition to ApoE immunoreactivity in Aβ plaques and in Aβ plaque-associated neurites in tissue from epilepsy, ApoE expression was also evident in neurons in all regions examined without regard to the presence of Aβ plaques." (PMID 22502727, 2012).
epilepsy (continued). "This might be inferred from studies reporting earlier onset of epilepsy, especially following traumatic brain injury in patients with APOE ε4 alleles." (PMID 22502727, 2012). "In contrast to the epilepsy-associated increase in IL-1α mRNA in patients of both genotypes, IL-1α protein measured by Western blot showed much greater elevation of IL-1α protein in APOE ε3,3 patients than that in APOE ε4,4 patients." (PMID 22502727, 2012). "Moreover, iPSCs derived from patients with mutations in lipid-related genes such as ApoE, and neurological conditions affecting neuronal synchronization such as epilepsy, might help deepen our understanding of these pathological conditions." (PMID 40502702, 2025). "This may help explain the known associations of APOE-ε4 with memory deficits and severe epilepsy." (PMID 35733430, 2022). "Traumatic brain injury (TBI), which is a major risk factor for the development of epilepsy, is also associated with increased risk for later development of AD, and, in both cases, the risk of development of AD is greater with inheritance of apolipoprotein E ε4 alleles (APOE ε4)." (PMID 24252240, 2013). "Conversely, a better understanding of mechanisms by which APOE ε3 alleles confer the neuronal protection shown here may facilitate development of therapeutic strategies toward improving outcomes for epilepsy patients, as well as patients with other neuronal distresses." (PMID 22502727, 2012). "With an eye toward defining ways in which APOE ε3 alleles may foster neuronal well-being in epilepsy and/or APOE ε4 alleles exacerbate neuronal decline, neuronal and glial characteristics were studied in temporal lobectomy specimens from epilepsy patients of either APOE ε4,4 or APOE ε3,3 genotype." (PMID 22502727, 2012). "In addition, our findings are consistent with the idea that as neurons with APOE ε4 alleles are less resilient to the chronic excitation of epilepsy and more susceptible to DNA damage, patients who carry APOE ε4 alleles are at greater risk of developing AD than are those with APOE ε3 alleles." (PMID 22502727, 2012). "Overall, these findings underscore the important role of APOE in modulating hippocampal metabolism during epilepsy, further complementing our understanding of the molecular mechanisms underlying the ketogenic diet's effects on TLE." (PMID 41085045, 2026). "Through its active involvement in microglial differentiation and other processes, APOE influences epilepsy progression in multiple ways." (PMID 41085045, 2026). "Overall, these findings suggest that APOE deletion attenuates the severity of KA‐induced epilepsy, whereas APOE overexpression in microglia exacerbates TLE progression and prolongs seizure duration." (PMID 41085045, 2026). "In epilepsy, both astrocytes and neurons exhibit upregulated APOE gene expression; however, their relative contributions decrease when compared with other cell types." (PMID 41085045, 2026). "This study aimed to explore the association between the apolipoprotein E (APOE) ε4 allele and cognitive function in older people with epilepsy." (PMID 40405274, 2025). "By contrast, in other types of brain diseases such as epilepsy, APOE genotype resulted to be a strong modifying factor in terms of both neuronal and glial neuropathological changes." (PMID 30677746, 2019). "Allelic combinations of APOE influenced each epilepsy-related neuronal and glial response measured as well as neuropathological change." (PMID 24252240, 2013). "Our results show that, compared to other APOE allelic combinations, neuronal resilience and glial activation were greatest in epilepsy patients with APOE ε3,3 genotype." (PMID 24252240, 2013). "Tissues from patients undergoing temporal lobectomies for drug-resistant epilepsy reveal APOE genotype-specific links between glial and neuronal stress responses." (PMID 22502727, 2012).
epilepsy (continued). "As to the total number of microglia per 0.037 mm2 in tissue from epilepsy patients with APOE ε3,3 vs APOE ε4,4 genotype (37.2 ± 10.6 vs 23 ± 5.7; P < 0.05)." (PMID 22502727, 2012). "To assess the consequences of epilepsy and APOE genotype on neurons, we counted neurons in cortical layers III to VI of three specific areas of the temporal lobe." (PMID 22502727, 2012). "These elevations in the levels of both IL-1α mRNA and protein were accompanied by an APOE ε3,3 genotype-specific increase in βAPP expression in epilepsy patients compared to controls (APOE ε3,3 = 42 ± 11 vs APOE ε4,4 = 20 ± 11; and control = 21 ± 7; P = 0.03)." (PMID 22502727, 2012). "Compared with the APOE−/−+KA group, significant upregulation was identified in metabolic pathways such as glycine, serine, and threonine metabolism; glycerophospholipid metabolism; and the pentose phosphate pathway within the WT+KA epilepsy model." (PMID 41085045, 2026). "Subsequently, we investigated whether APOE and APOE‐overexpressing microglia enhance neuronal firing and exacerbate chronic epilepsy pathology in animal models." (PMID 41085045, 2026). "The APOE ε4 allele has been associated with an increased risk of drug-resistant epilepsy, but other studies have failed to prove this relationship in patients with TLE from Italy or patients with TLE from Turkey without HS." (PMID 39337715, 2024). "Some of these genes have been reported in epilepsy studies, for example, APOE." (PMID 39727961, 2024). "Taken together, our findings suggest that APOE genotype may be important in decisions regarding timing of surgical intervention for intractable epilepsy, as well as in decisions regarding exposure of individuals to activities with high risk for TBI." (PMID 24252240, 2013). "Evidence of a role for APOE genotype in determining neurodegenerative consequences of epilepsy underscores the need for in-depth analyses of neuronal-glial interactions that may be governed by inheritance of specific APOE allelic combinations." (PMID 24252240, 2013). "Exploring possible links between epilepsy-related alterations in neuronal and glial cell responses relative to APOE genotype is potentially important in understanding chronic neurodegenerative sequelae in epilepsy as well as in other forms of brain injury such as TBI." (PMID 24252240, 2013). "The cross-sectional area of APOE ε4,4 neurons was less than that of APOE ε3,3 neurons in both epilepsy and Alzheimer patients, perhaps suggesting that APOE ε4,4 neurons are not able to follow the same response to neuronal stress as do neurons of other genotypes." (PMID 24252240, 2013). "An initial screening of 59 epilepsy patients (52 APOE ε3,3; 7 APOE ε4,4) and 5 neurologically normal controls revealed an observable elevation in numbers of microglia per neuron soma in brain tissue from epilepsy patients compared to that in brain tissue from controls (data not shown)." (PMID 22502727, 2012). "Connections among APOE genotype, epilepsy and AD have been drawn, but mechanisms by which the APOE ε4,4 genotype heightens intensity of neuronal damage or, conversely, how the APOE ε3,3 genotype may act to promote neuronal resilience remains unclear." (PMID 22502727, 2012). "Although APOE ε4 seems to be a risk factor for epilepsy, we could not find any significant differences regarding APOE ε4 carrier status between AD patients with SEA versus those without." (PMID 38263073, 2024). "Thus, there are functional inks between HSE sequelae and AD, links between AD and epilepsy, and HSE and epilepsy, probable links between epilepsy and herpes viruses, possible links of epilepsy also with specific APOE alleles, and much evidence linking HSV1 to AD." (PMID 30405395, 2018).
epilepsy (continued). "To assess the neuronal response to the hyperexcitation stress in epilepsy, we measured the relative tissue levels of the messenger RNAs for both βAPP and ApoE in tissue samples from patients (n = 92) with each of the different APOE allelic combinations, using real time PCR analysis." (PMID 24252240, 2013). "Furthermore, the potential of such a cycle to be self-regenerative may explain, at least in part, why even those epilepsy patients with the advantage of an APOE ε3,3 genotype may develop Alzheimer-type neuropathological changes." (PMID 24252240, 2013). "There have been a number of studies specifically on the involvement of APOE, and also of HSV1 and HHV6, in epilepsy." (PMID 30405395, 2018). "Studies on the link between epilepsy, AD and herpes simplex encephalitis (HSE) are described also, as are the possible roles of APOE-ε4, HHV6 and HSV1 in epilepsy." (PMID 30405395, 2018). "Precocious development of Alzheimer-type neuropathological changes in epilepsy patients, especially in APOE ε4,4 carriers is well known, but not the ways in which other APOE allelic combinations influence this outcome." (PMID 24252240, 2013). "APOE ε4,4 conferred the weakest neuronal resilience in epilepsy as well as in Alzheimer patients, but there were no APOE genotype-dependent differences in these parameters in neurologically normal patients." (PMID 24252240, 2013). "No APOE genotype-related changes in neuronal cell numbers were detected in our epilepsy patient Groups 1,2,3, and 4 (302 ± 39, 277 ± 25, 280 ± 32, 272 ± 21 per mm2, respectively)." (PMID 24252240, 2013). "This influence of APOE genotype in epilepsy appears to occur without regard to gender or age at the time of surgery." (PMID 22502727, 2012). "No APOE ε4 allele interaction effect was found in patients with TA-TLE, indicating that mechanisms involving tau phosphorylation are not relevant in tumor-associated epilepsy." (PMID 39337715, 2024). "The Unified Myoclonus Rating Scale (UMRS), Quality of Life in Epilepsy Inventory-31 questionnaire (QOLIE-31), intellectual ability (WAIS-R), clinical data, and quantitative neuroimaging data were compared between APOE ε4 carriers and noncarriers to assess potential correlations with EPM1 severity." (PMID 41042579, 2025).